TSTD1 (thiosulfate sulfurtransferase like domain containing 1)
Description:
Thiosulfate:glutathione sulfurtransferase (TST) required to produce S-sulfanylglutathione (GSS(-)), a central intermediate in hydrogen sulfide metabolism. Provides the link between the first step in mammalian H(2)S metabolism performed by the sulfide:quinone oxidoreductase (SQOR) which catalyzes the conversion of H(2)S to thiosulfate, and the sulfur dioxygenase (SDO) which uses GSS(-) as substrate. The thermodynamic coupling of the irreversible SDO and reversible TST reactions provides a model for the physiologically relevant reaction with thiosulfate as the sulfane donor. GSS(-) spontaneously reacts with glutathione to form glutathione disulfide (Probable).
Synonyms: KAT
Tractability: PROTAC: its protein half-life has been measured.
Gene: Protein-coding gene on chromosome 1 (161,037,631 to 161,038,977, reverse strand). Ensembl gene ENSG00000215845.
Subcellular location: Cytoplasm, perinuclear region
Subcellular location (Human Protein Atlas): Cytoplasmic bodies; Cytosol
Pathways (Reactome):
Metabolism: Sulfide oxidation to sulfate
Gene Ontology:
Molecular function: thiosulfate-thiol sulfurtransferase activity
Biological process: sulfide oxidation
Cellular component: cytoplasm; cytosol; perinuclear region of cytoplasm
Genetic constraint (gnomAD): Loss-of-function variants: 7 observed, 14.32 expected, observed/expected ratio (o/e) 0.49, 90% interval 0.28 to 0.92. The upper end of that interval is the gene's LOEUF score, 0.92, which puts it in group 3 of 6, group 1 being the genes least tolerant of losing a copy. Missense variants: 156 observed, 154.2 expected, observed/expected ratio (o/e) 1.01, 90% interval 0.89 to 1.15. Synonymous variants: 73 observed, 62.58 expected, observed/expected ratio (o/e) 1.17, 90% interval 0.96 to 1.42.
Homologues: Orthologues: chimpanzee TSTD1 (99% identical), macaque TSTD1 (98% identical), guinea pig TSTD1 (89% identical), pig TSTD1 (88% identical), rabbit TSTD1 (86% identical), dog TSTD1 (85% identical), mouse Tstd1 (83% identical), zebrafish tstd1 (49% identical). Paralogues in human: CEP41 (23% identical).
Diseases named in the same sentence as TSTD1 in open-access papers:
TSTD1 is named in the same sentence as 17 diseases in open-access papers, as found by Europe PMC text mining. Sharing a sentence is not in itself a finding about the gene and the disease. The quoted sentences say what the papers report.
breast carcinoma (1 paper, 2022). "Overexpression of TSTD1 mRNA was associated with the histological type and tumor stage of patients with breast cancer (p < 0.001 and 0.040, respectively)." (PMID 36419875, 2022). "Overexpression of TSTD1 in tumors of breast cancer patients was significantly associated with poor 5-year overall survival (p = 0.021) and poor chemotherapy response (p = 0.008)." (PMID 36419875, 2022). "A multivariate Cox proportional hazards survival analysis revealed that TSTD1 mRNA expression in patients with breast cancer was significantly associated with poor 5-year overall survival in TCGA data (p = 0.021), especially in patients with negative ER/PR expression (p = 0.008)." (PMID 36419875, 2022). "This is most likely why decreased ROS levels were observed after TSTD1 knockdown in breast cancer cells." (PMID 36419875, 2022). "These previous studies support the idea that decreases in estrogen and ROS levels are the mechanism for decreased breast cancer cell proliferation after TSTD1 knockdown." (PMID 36419875, 2022). "Here we found the protein expression level of TSTD1 is significantly higher in invasive breast tumors of Taiwanese and Korean breast cancer patients." (PMID 36419875, 2022). "The results are consistent with the TCGA cohort data, where TSTD1 overexpression is correlated with poor drugs treatment response in breast cancer patients." (PMID 36419875, 2022). "High TSTD1 mRNA expression was correlated with the poor drugs treatment response in Western patients with breast cancer patients (p = 0.030), especially for chemotherapy drug response (p = 0.005)." (PMID 36419875, 2022). "Hypomethylation and overexpression of TSTD1 were found specifically in the breast cancer tissues of patients in Asain and Western countries." (PMID 36419875, 2022). "Circulating cell-free hypomethylated TSTD1 can be detected in all the breast cancer patients (n=12)." (PMID 36419875, 2022). "High expression of TSTD1 protein was observed in 68.8% of Taiwanese and Korean breast cancer patients." (PMID 36419875, 2022). "Circulating cell-free hypomethylated TSTD1 was detected in plasma of Taiwanese breast cancer patients with disease progression and poor chemotherapy efficacy." (PMID 36419875, 2022). "Using the methylation array data and The Cancer Genome Atlas (TCGA) dataset, we observed the hypomethylation and upregulation of thiosulfate sulfurtransferase–like domain containing 1 (TSTD1) in patients with breast cancer." (PMID 36419875, 2022). "This study examined the methylation and gene product expression of TSTD1 in Taiwanese and Western patients with breast cancer." (PMID 36419875, 2022). "Cox proportional hazard model of clinical parameters and TSTD1 mRNA expression level in TCGA breast cancer." (PMID 36419875, 2022). "Breast tumor samples from Taiwanese and Korean breast cancer patients were stained with a TSTD1 antibody for immunohistochemical analysis." (PMID 36419875, 2022). "TSTD1 promoter hypomethylation, mRNA and protein overexpression in breast cancer tissues obtained from Asian patients." (PMID 36419875, 2022). "Analysis of RNA sequencing data obtained from TCGA revealed that 69.4% (50/72) of patients with breast cancer had significant TSTD1 mRNA upregulation in tumors compared with adjacent normal tissues." (PMID 36419875, 2022). "This study investigated changes in TSTD1 methylation and expression in patients with breast cancer compared to normal tissues to determine the potential of TSTD1 as a tumor biomarker in clinical practice in breast cancer." (PMID 36419875, 2022). "To determine alteration in TSTD1 hypomethylation and mRNA expression in Western patients with breast cancer, we analyzed the TCGA data of 87 breast tumors, 87 matched normal tissues, and 643 breast tumor tissues." (PMID 36419875, 2022).
breast carcinoma (continued). "Our results indicate that promoter hypomethylation and overexpression of TSTD1 in patients with breast cancer are potential biomarkers for poor 5-year overall survival and poor treatment response." (PMID 36419875, 2022). "TSTD1 mRNA expression and methylation levels in relation to the clinical parameters of Western with breast cancer." (PMID 36419875, 2022). "The results are consistent with the clinical data, where TSTD1 overexpression in Western and high TSTD1 protein expression in Taiwanese are correlate with increased estrogen levels in patients with breast cancer." (PMID 36419875, 2022). "We identified thiosulfate sulfurtransferate-like domain containing 1 (TSTD1) as a potential biomarker specific to breast cancer." (PMID 36419875, 2022). "In addition, a previous study revealed that TSTD1 was the only hypomethylated gene related to HER2+ breast cancer patients." (PMID 36419875, 2022). "Overexpression of TSTD1 mRNA was associated with negative ER and negative progesterone receptor (PR) expression in patients with breast cancer (p < 0.001)." (PMID 36419875, 2022). "In this study, liquid chromatography–mass spectrometry LC–MS was used to determine whether TSTD1 is involved in glutathione-dependent sulfide oxidation reaction in the T47D breast cancer cell line." (PMID 36419875, 2022). "In addition, ESR1 expression significantly decreased after TSTD1 knockdown and significantly increased after transfection of TSTD1 in separate breast cancer cell lines." (PMID 36419875, 2022). "In addition, hypomethylation of TSTD1 in cell-free DNA can be detected in breast cancer patients with poor chemotherapy efficacy and disease progression." (PMID 36419875, 2022). "Notably, hypomethylation of TSTD1 was stronger in TCGA Asian patients with breast cancer compared with Taiwanese patients with breast cancer, most likely due to technological differences or environmental interference in the different countries." (PMID 36419875, 2022). "Furthermore, through analyzing TCGA datasets, we found promoter hypomethylation and overexpression of TSTD1 in patients with breast cancer, even in Asian patients with breast cancer." (PMID 36419875, 2022). "Immunohistochemical analysis revealed strong expression of TSTD1 protein in the tumor tissue of patients with breast cancer; however, weak to no staining was noted in normal tissues." (PMID 36419875, 2022). "We collected paired samples of cancerous and adjacent noncancerous tissue from Taiwanese patients with breast cancer for molecular studies to determine alterations in TSTD1 methylation and expression." (PMID 36419875, 2022). "Previous studies have shown TSTD1 is highly expressed in breast cancer cell lines but not in normal breast cell lines." (PMID 36419875, 2022). "However, overexpression of TSTD1 mRNA expression only was found in breast cancer patients, but not in lung cancer patients." (PMID 36419875, 2022).
breast tumor (1 paper, 2022). "The analysis of data from TCGA and Taiwanese revealed significantly decreased TSTD1 methylation levels in breast tumors compared with adjacent normal tissues." (PMID 36419875, 2022). "Circulating cell-free hypomethylated TSTD1 was found to be higher in breast tumors of patients who displayed distant metastasis after treatment." (PMID 36419875, 2022). "The CpG site cg24161057, which is on the promoter of TSTD1, was hypomethylated in 77.0% (67/87) of breast paired tissues and 81.0% (521/643) of non-paired breast tumor tissues." (PMID 36419875, 2022).
carcinoma in situ (1 paper, 2022). "In general, the intensity of TSTD1 staining increased from normal to lobular to carcinoma in situ tissues, becoming the highest in invasive carcinoma tissues." (PMID 36419875, 2022).
clear cell sarcomas of the kidney (1 paper, 2022). "TSTD1 was the only gene methylated at significantly different (higher) levels in three tumor types: clear cell sarcomas of the kidney, osteosarcomas, and rhabdoid tumors." (PMID 35707123, 2022).
colon cancer (1 paper, 2021). "TST like domain-containing 1 (TSTD1) might play a role in sulfide-based signaling and overexpression in colon cancer." (PMID 34130650, 2021).
ductal carcinoma in situ (1 paper, 2022). "Within cancerous tissues, TSTD1 staining was more robust in invasive areas than ductal carcinoma in situ." (PMID 36419875, 2022).
lung carcinoma (1 paper, 2022). "Additional clinical studies with a larger sample size are needed to provide a detailed analysis of the function of TSTD1 in lung cancer." (PMID 36419875, 2022). "Upon examining the alterations of TSTD1 in different types of cancer, we found TSTD1 was hypomethylated in lung cancer samples from both the TCGA cohort and Taiwanese patients." (PMID 36419875, 2022). "In our study, siRNA knockdown of TSTD1 in the H1299 lung cancer cell line suppressed cell growth." (PMID 36419875, 2022). "Therefore, we concluded that the relationship between TSTD1 expression and methylation in patients with lung cancer depended on other conditional factors in the individual." (PMID 36419875, 2022). "Hypomethylation of TSTD1 was observed in Western and Taiwanese breast and lung cancer patients." (PMID 36419875, 2022). "Additionally, a study reported TSTD1 expression in lung cancer cell models." (PMID 36419875, 2022).
neuroblastoma (1 paper, 2022). Neuroblastoma (NB) is the most common solid, extracranial childhood tumor. "These included the top MYCNARB1PRO downregulated TSTD1 and CDKN2C genes, which also showed a significantly lowered expression in MYCN-amplified compared with the MYCN-silent neuroblastomas." (PMID 36245757, 2022).
retinoblastoma (1 paper, 2022). A malignant tumor that originates in the nuclear layer of the retina. "TSTD1, CDKN2C, NUCB2, and KATNAL1 showed the most significant MYCNARB1PRO-specific downregulated expression pattern among the hypermethylated genes in this retinoblastoma subtype." (PMID 36245757, 2022).
tumor (2 papers, 2022). "Of the paired samples, 68.3% (43/63) exhibited higher TSTD1 mRNA expression in tumor tissues than in the paired normal tissues." (PMID 36419875, 2022). "Finally, the hypomethylation and overexpression of TSTD1 are potential biomarkers for tumor proliferation and chemotherapy and hormone therapy drug response." (PMID 36419875, 2022).
cancer (1 paper, 2022). A tumor composed of atypical neoplastic, often pleomorphic cells that invade other tissues. "However, no comprehensive study has evaluated underlying alterations in TSTD1 in cancer and its applications in clinical practice." (PMID 36419875, 2022). "In Western cohorts, most of the patients with ER- and PR-positive cancer exhibited TSTD1 overexpression." (PMID 36419875, 2022). "In conclusion, TSTD1 is a potential biomarker for cancer outcomes: alterations of TSTD1 could indicate poor drug treatment response and 5-year survival." (PMID 36419875, 2022).
TSTD1 also shares sentences with these, for which no sentence is quoted: invasive carcinoma (1 paper); lung adenocarcinoma (1); lung squamous cell carcinoma (1); osteosarcoma (1); pancreatic cancers (1); rhabdoid tumor (1).